RNU7-157P (RNA, U7 small nuclear 157 pseudogene)
Gene: Small nuclear RNA gene on chromosome 7 (57,227,001 to 57,227,066, forward strand). Ensembl gene ENSG00000238431.
Homologues: Orthologues: chimpanzee U7 (100% identical). Paralogues in human: RNU7-57P (77% identical), RNU7-11P (76% identical), RNU7-79P (76% identical), RNU7-143P (74% identical), RNU7-173P (74% identical), RNU7-2P (74% identical), RNU7-3P (74% identical), RNU7-52P (74% identical), RNU7-60P (74% identical), RNU7-67P (74% identical), RNU7-80P (74% identical), RNU7-92P (74% identical), and 142 more.